ZFP37 (ZFP37 zinc finger protein)
Description:
May be involved in transcriptional regulation.
Synonyms: Zfp-37; ZNF906
Tractability: PROTAC: ubiquitination databases record sites on it.
Gene: Protein-coding gene on chromosome 9 (113,038,377 to 113,056,759, reverse strand). Ensembl gene ENSG00000136866.
Subcellular location: Nucleus
Subcellular location (Human Protein Atlas): Nucleoplasm; Vesicles
Pathways (Reactome):
Gene expression (Transcription): Generic Transcription Pathway
Gene Ontology:
Molecular function: DNA-binding transcription factor activity; DNA-binding transcription factor activity, RNA polymerase II-specific; RNA polymerase II transcription regulatory region sequence-specific DNA binding; zinc ion binding; sequence-specific double-stranded DNA binding
Biological process: regulation of DNA-templated transcription; regulation of transcription by RNA polymerase II
Cellular component: nucleus
Genetic constraint (gnomAD): Loss-of-function variants: 39 observed, 55 expected, observed/expected ratio (o/e) 0.71, 90% interval 0.55 to 0.93. The upper end of that interval is the gene's LOEUF score, 0.93, which puts it in group 3 of 6, group 1 being the genes least tolerant of losing a copy. Missense variants: 695 observed, 779.6 expected, observed/expected ratio (o/e) 0.89, 90% interval 0.84 to 0.95. Synonymous variants: 253 observed, 274.84 expected, observed/expected ratio (o/e) 0.92, 90% interval 0.83 to 1.02.
Homologues: Orthologues: chimpanzee ZFP37 (98% identical), macaque ZFP37 (95% identical), rabbit ZFP37 (79% identical), guinea pig ZFP37 (71% identical), rat Zfp37 (70% identical), mouse Zfp37 (69% identical), rat Zfp37-ps1 (66% identical), rat AABR07048473.1 (60% identical), Drosophila melanogaster CG3281 (23% identical), Drosophila melanogaster Phs (19% identical), Drosophila melanogaster CG2712 (19% identical). Paralogues in human: ZNF10 (38% identical), ZFP90 (37% identical), ZNF805 (37% identical), ZNF266 (36% identical), ZNF614 (36% identical), ZNF25 (36% identical), ZNF599 (36% identical), ZNF264 (35% identical), ZNF778 (35% identical), ZNF674 (35% identical), ZNF248 (34% identical), ZNF582 (34% identical), and 50 more.
Diseases named in the same sentence as ZFP37 in open-access papers:
ZFP37 is named in the same sentence as 1 disease in open-access papers, as found by Europe PMC text mining. Sharing a sentence is not in itself a finding about the gene and the disease. The quoted sentences say what the papers report.
cancer (2 papers, 2013 to 2025). A tumor composed of atypical neoplastic, often pleomorphic cells that invade other tissues. "The highest relative expression of zfp37 showed grade I tumors (0.0031 ± 0.0008), whereas the lowest expression exposed the most malignant tumors (0.0012 ± 5.5e-005)." (PMID 23844591, 2013). "MIPEP expression was also significantly increased (p < 0.05) in grade II tumors comparing to the grade I. We also showed significantly (p < 0.05) and highly significant (p < 0.001) decreased expression of MAGI3 and ZFP37 (respectively) in the most malignant tumors." (PMID 23844591, 2013).